IFNG (interferon gamma)
Diseases named in the same sentence as IFNG in open-access papers (continued):
Sharing a sentence is not in itself a finding about the gene and the disease.
infection (continued). "First, the presence of Nb during STm infection has virtually no impact on IFNγ production, suggesting that the pro-inflammatory cytokine profile and possibly its anti-Th2 activities would be retained." (PMID 25474738, 2014). "Presence of irrelevant non-targeting shRNA against lacZ or luciferase did not affect the IFNγ-mediated inhibition of HSV-GFP infection." (PMID 25268627, 2014). "The increased lethality appeared to result from an elevation in key pro-inflammatory cytokines and chemokines, such as IL-6, IFNγ and MCP-1; whilst in the latter phase of the infection, Socs4R108X/R108X mice displayed impaired trafficking of virus-specific CD8 T cells to the lungs." (PMID 24809749, 2014). "Of the cytokines/chemokines studied only IFNγ, IP-10, MIG, MCP-1, IL-17 and IL-6 showed measurable shifts in concentration that could be related to infection and or treatment." (PMID 23469125, 2013). "We also observed a slight increase in IFNγ+ lamina propria CD4+ T-cells in Itgb8 (CD11c-Cre) mice early post-infection; however, these levels were not significantly different from those seen in control mice." (PMID 24098124, 2013). "Seminal studies on experimental infections of Leishmania major in C57BL/6 and BALB/c inbred mouse strains correlated parasite control with the elaboration of interferon gamma (IFN-γ) by CD4+ T cells and uncontrolled infections with the absence of IFN-γ in the C57BL/6 and BALB/c mice, respectively." (PMID 23801993, 2013). "Type II IFN (IFNγ) did not pass the initial filtering for genes expressed above background and was not induced upon infection (not shown)." (PMID 24278020, 2013). "In contrast, although there was a slight enhancement of the Th1 cytokine IFNγ 3 days post-infection, this was not significantly different between control and Itgb8 (CD11c-Cre) mice." (PMID 24098124, 2013). "Unexpectedly, we were unable to detect an IFNγ response in the spleen or MdLN following SL immunization with MOMP plus CT/CpG, even though this group of animals was significantly protected against infection." (PMID 23613984, 2013). "T cell proliferation and IFNγ production by splenocytes was greater in WT animals following in vitro re-stimulation, however vaccination was only effective at reducing infection in WT, not IL-17-/- mice." (PMID 24073293, 2013). "This is in contrast to infections with the lineage I New York strain (WNV-NY), which results in increased susceptibility in the absence of IFNγ." (PMID 24153060, 2013). "Within the IFN-I-regulated cytokine milieu IFNγ, an important determinant of innate immunity, becomes limiting in the early phase of i.g. infection, particularly in absence of other IFN-I-regulated protective proinflammatory cytokines/chemokines." (PMID 23840314, 2013). "Together, these changes were accompanied by a significantly reduced production of IFNγ (6 days post-infection) by splenocytes ex vivo measured under non-stimulated conditions (4–5×decrease), or in response to PMA/ionomycin, or to IL12p70 treatment." (PMID 23853600, 2013). "During infections in neonates, the clearance of the parasite was preceded by a rapid recruitment of CD103+ DC mediated by CXCR3-binding chemokines produced by IEC in response to IFNγ." (PMID 24367259, 2013). "Additionally, IFNγ-induced CIM cells died by reactive cell death after infection with both virulent RH-YFP and avirulent ME49, while BL/6 cells died only after infection with avirulent strains." (PMID 24175088, 2013). "Of the 23 analytes measured in this study, all but 6 (IFNγ, IP-10, MIG, MCP-1, IL-17 and IL-6) showed no discernible association with 4–9 weeks infection or with chemotherapy." (PMID 23469125, 2013). "Of further interest, early splenic IFNγ production was increased in Ifnar1−/− mice compared to Wt after i.p. infection, but not after infection through the gastrointestinal tract." (PMID 23840314, 2013).
infection (continued). "To evaluate whether primed neutrophils are more resistant to IAV replication, we primed neutrophils with PAR2 agonist, IFNγ, or their combination for 2 hrs before cells were infected with IAV and rechallenged cells after infection (b/a-stimulation)." (PMID 24171176, 2013). "In Nos2−/− mice that were infected with DENV, no clinical signs of infection were observed and cytokines were expressed at low levels, with the exception of interferon gamma (Ifng)." (PMID 23978258, 2013). "At the late stage of in vitro infection (48 HPI), however, the IFNγ expression level increased." (PMID 23711280, 2013). "On the other hand, infection with 2W1S-expressing L. monocytogenes induced no IFNγ expression among 2W1S-specific CD4 T cells in postpartum females that had delivered 2W1S+ pups." (PMID 24391885, 2013). "Infection of mice with Mycobacterium tuberculosis followed by repeated BCG injections led to an IL-17A–dominated response, which was refractory to regulation by IFNγ." (PMID 23457650, 2013). "Strikingly, adoptive transfer of wild-type but not Ifnγ−/− CD4+ T lymphocytes into Cxcr3−/− animals prior to infection corrected the defect in inflammatory macrophage activation, simultaneously reversing the susceptibility phenotype of the knockout animals." (PMID 24130498, 2013). "Cytokines with a clear response to the infection and/or a different response in the vaccinated and non-vaccinated chickens included iNOS, IFNγ, IL17 and IL22." (PMID 22384225, 2012). "IFNγ levels were significantly reduced in all infected TLR−/− strains, most significantly in TLR2−/− mice, and may have contributed to enhanced infection in TLR2−/− pups." (PMID 22724018, 2012). "To begin to define the cellular pathways and/or gene products that inhibit S. flexneri replication in MEFs, we first tested whether IRF1 is induced by IFNγ during infection and whether IRF1 contributes to IFNγ-mediated restriction of this bacterium." (PMID 22912573, 2012). "RSK1 is also involved in regulation of IFNγ-dependent translation; however, such a role was not evident at 16 h of infection, when we characterized chemokines/cytokines present in serum and produced by CD11b+ cells." (PMID 23248776, 2012). "Hence, HCV-core specific T cells secreting IFNg can play a major role in prevention and treatment of the HCV-infection." (PMID 22879829, 2012). "Conversely, infection of neonatal mice with the same weight-based dose of RSV resulted in an absence of IFNγ, coupled with increases in IL-4 and IL-10." (PMID 22792355, 2012). "The impact of the absence of Notch on T cells in the differentiation of CD4+ IFNγ-secreting Th1 cells was assessed six weeks after infection." (PMID 22396647, 2012). "Without this early IFNγ production, naïve mice infected with HSV-2 become more susceptible to the infection." (PMID 22457721, 2012). "As a result, the iNKT subset is maintained following infection and exhibits no impairment in IFNγ production." (PMID 22916008, 2012). "In contrast, both KOS and JD0G infection nearly eliminated IDO expression in IFNγ-treated SNB19 cells, and 1-MT did not improve virus replication." (PMID 22924042, 2012). "Peripheral blood mononuclear cells (PBMCs) from some (but not all) individuals with subclinical or asymptomatic infection respond to stimulation with leishmanial antigen (LAg) and produce IL-2, IFNγ, and IL-12." (PMID 22912637, 2012). "As expected, due to its antiviral effects, IFNγ treatment reduced HIV-1Bal-L production measured at day seven post-infection from a median of 1040 cpm in the absence of priming to 599 cpm with priming (p = 0.004)." (PMID 22363802, 2012). "As production of interferon gamma by these cells is contested, it is possible that the generation of CXCL10 is either a direct effect of NiV proteins or is induced via NiV-activation of interferon beta, following infection." (PMID 22393386, 2012).
infection (continued). "This suggests that N1 is the main receptor involved in signaling leading to the induction of IFNγ secretion by T cells following infection with L. major, but that in absence of N1, higher levels of N2 can compensate its absence." (PMID 22396647, 2012). "It was previously shown that infection with a Pru(II) strain of Toxoplasma does not interfere with IFNγ induced serine phosphorylation of STAT1 in HFFs, but this has not been shown for any type I or III strains." (PMID 23240025, 2012). "Consistent with the increase in IFNγ+ NK1.1+CD3- cells seen after in vivo L1S stimulation, we observed a significant increase in serum IFNγ levels in the mice treated with L1S prior to Ft infection." (PMID 22072975, 2011). "While IFNγ was progressively upregulated throughout the infection, several other genes in the IFNγ network were not." (PMID 22645653, 2011). "In our study expression of IFNγ was upregulated in all mice after infection, and there was only a decrease in viral replication in immunized mice indicating that IFNγ did not play a significant role in protection." (PMID 21949840, 2011). "IFNγ was not detectable in either1x or 4x mice, while only limited amounts of IL-10 were detected, supporting thethesis that multiple infections induce lymphoid hypo-responsiveness." (PMID 21445234, 2011). "While, generation of effector cytokines, such as IFNγ and TNFα by the Th1 cells are known to be crucial for the resolution of M. tuberculosis infection, IL2 production by these T helper cells aids in the maintenance of memory immunity against infection." (PMID 21533158, 2011). "Previous to the infection, analyzing the mononuclear cells isolated from Peyer's patches, it was observed that mice fed 7 days with L. casei CRL 431 significantly increased cytokines expression and also the release of IFNγ and IL-10 by these cells." (PMID 21813005, 2011). "Given that IFNγ has been shown to regulate the ability to clear LCMV infection, this initial decrease in IFNγ at the early stage of infection could result in a reduced ability to control viral replication, leading to further CD8 T cell exhaustion." (PMID 21814510, 2011). "Another study employing IFNγ−/− mice demonstrated that infection with Bordetella pertussis was exacerbated in the absence of IFNγ." (PMID 21738466, 2011). "In contrast, the EI8 epitope was recognised by the EI8-specific CTL clones, which generated a detectable IFNγ response that was significantly different (p<0.001) between FL8- and EI8-specific clones at 48, 72 and 96 hours post-infection in a 2-way ANOVA with bonferroni post-test." (PMID 21589893, 2011). "In the present study, there was a rapid shift from a Th1 immune response characterised by the expression of IFNγ and IL-1β genes to a regulated Th2 immune response characterised by the expression of IL-13, IL-10, TGFβ, and FOXP3 genes by seven days post infection (dpi) in the carrier lambs." (PMID 21385411, 2011). "Specifically, we compared the induction of several pro-inflammatory cytokines (TNFα, IL6, IFNγ and MCP1) for changes in expression during infection by analyzing lung homogenates by CBA or quantitative RT-PCR to measure levels of mRNAs in Urbani virus or rMA15 virus infected mice, respectively." (PMID 20386712, 2010). "In contrast to control DCs, infection of hepatic DCs restored the alterate capacity of non-infected liver DCs to stimulate allogeneic T cell proliferation and IFNγ secretion." (PMID 20544029, 2010). "This course of infection was correlated with an early TH1 type, cellular immune response, characterized by the production of specific cytokines, such as interleukin (IL)-12 and γ-interferon (IFNγ)." (PMID 20345655, 2010). "However, to our surprise, we found that upon infection with T. gondii, except for impaired IL-12p40 production, 3d mice showed high levels of IL-6, MCP-1, IFNγ, and TNFα in their sera." (PMID 20865117, 2010).
infection (continued). "Consistent with the delayed production of IL-12, we also observed a late IFNγ response by spleen or peritoneal exudate cells from 3d mice, which was lower on days three and five, but not on days seven or eight post-infection." (PMID 20865117, 2010). "We found that IL-2Jc administered on the day of infection resulted in lower serum IFNγ levels by day 4 p.i., whereas neither IL-2Sc nor delayed IL-2Jc treatment had any significant effect." (PMID 21170302, 2010). "Upon infection of both murine and peripheral monocyte-derived human DCs with either Mtb or BCG in vitro and in vivo, DCs matured, produced Th1-promoting cytokines, and induced IFNγ-producing T cells." (PMID 20625513, 2010). "Thus, IFNγ not only exhibits pro-inflammatory characteristics during progression of active periodontal lesions, but may also promote protective capabilities in the early stage of infection by increasing the gene expression of hBD1 and hBD3 in HOKs carrying the common -44 CC genotype." (PMID 19712472, 2009). "Given our earlier studies on the essential role of CCL3 in eliciting neutrophil recruitment, it is interesting to note that the absence of IFNγ signaling had no impact on local production of this chemokine in response to PVM infection." (PMID 19298652, 2009). "In this study, we identify Irga6 as an important resistance factor against C. trachomatis, but not C. muridarum, infection in IFNγ-stimulated mouse embryonic fibroblasts (MEFs)." (PMID 19242543, 2009). "Maximal PPD specific IFNγ levels post-vaccination, but not post-infection, showed a significant and inverse correlation with total PA (Rs = −0.49, p = 0.0140)." (PMID 19367339, 2009). "In co-infected, IFNγ-induced MEFs transfected with Cherry as a fluid phase marker and assayed at 4 hours after infection, the presence of the virulent RH-YFP had no impact on the permeabilisation of parasites, which reached the usual figure of over 20%." (PMID 19197351, 2009). "On the other hand, the pro-inflammatory chromatin binding protein, HMGB1, was detected as early as 2 h after infection in the supernatant of the IFNγ-induced, T. gondii infected cells but not in the supernatants of the cycloheximide and TNFα-treated cells." (PMID 19197351, 2009). "PPD- and ESAT6/CFP10 stimulation revealed highest IFNγ secretion in non-vaccinated controls in general at 6–8 weeks post-infection (respectively)." (PMID 19367339, 2009). "Surprisingly, even though the infections were performed in the absence of IFNγ and thus under conditions where Stat1 should be inactive, survival of both wild-type and lpg− promastigotes was increased in Stat1−/− PEMs by more than twofold." (PMID 19381261, 2009). "Contrarily, maximal IFNγ release upon Ag85A stimulation post-infection, but not post-vaccination, correlated significantly with disease by total PA lesion score (Rs = −0.60, p = 0.0018)." (PMID 19367339, 2009). "In contrast to PPD or ESAT6/CFP10 induced responses post-infection, there is no sign of reduced Ag85A specific IFNγ in the vaccinated versus non-vaccinated groups." (PMID 19367339, 2009). "ESAT6/CFP10 specific maximal IFNγ secretion, which was monitored in the post-infection phase only, did not correlate significantly with total PA at autopsy." (PMID 19367339, 2009). "Most important for the present study, the data also show that, very soon after infection, virus-derived peptides are presented to T cells at sufficient levels to induce memory cells to produce IFNγ, yet the cells do not initiate division." (PMID 18404208, 2008). "Within the testis, the levels of expression of the immunosuppressive cytokines IL-10 and TGFβ and pro-inflammatory cytokines IFNγ, IL-1β, TNFα transcripts was not significantly changed following infection." (PMID 18347738, 2008). "Similarly, infection of Kb−/−xDb−/− mice resulted in a significant increase in the proportion of PMA and ionomycin–stimulated cells that expressed IFNγ." (PMID 16733540, 2006).
infection (continued). "This pattern suggests a role for IFNγ in histopathology and restriction of infection, which is confirmed since histopathologic lesions do not develop in IFNγ knockout mice, but the mice have a 5- to 8-fold increase in bacteremia levels." (PMID 16485466, 2005). "Ex vivo restimulation 30 days after infection of splenic lymphocytes with mycobacterial antigens (SupBCG), but not with an irrelevant antigen, induced IFNγ secretion in cells from both TNF-KO and mem-TNF mice." (PMID 16285886, 2005). "Similarly, upregulation of IFNγ or CXCR6 upon re-infection proceeded normally in the absence of Myo1f (Fig 7Ci-ii)." (PMID 40132035, 2025). "Furthermore, infection led to an increase in the expression of cancer progression-related chemokines Ccl5 and Cxcl16, being upregulated most prominently by SFV/TNFα and SFV/IFNγ." (PMID 40547518, 2025). "In addition, CD4 + IFNγ+ cells were not significantly altered 3, 5, and 14 days after primary infection in the C. auris and C. albicans infection." (PMID 40294061, 2025). "Thus, the reduced Th1 responses and expression of IFNG, TNF, GZMB, and PRF1 in CD4+ Trms may indicate the impaired anti-infection capacity in COPD airways." (PMID 40589761, 2025). "However, humans lack TLR11/12 and IFNγ-inducible IRGs, and most of the Toxoplasma ROPs and GRAs that determine virulence in rodents play no role in human infection." (PMID 40667022, 2025). "Peripheral EHV-1 specific interferon-gamma (IFN-γ) producing CD8+ T-cells and CD4+ T-helper 1 (Th1) cells were induced after EHV-1 infection and vaccination, and their proportions in peripheral blood vary with time after infection, age, pregnancy, and vaccination." (PMID 40266191, 2025). "Although IFNγ deficiency did not increase bacterial burden at the height of the disease, IFNγ KO mice failed to increase MHCII on colonic epithelial cells and clear the infection." (PMID 39937862, 2025). "Interestingly, IFNγ knockout animals showed delayed bacterial clearance and survived the infection, yet mice lacking TNF succumbed to disease." (PMID 40415550, 2025). "These emergent differences in TNFα and IFNγ parameters between LTBI and naïve simulations could be reflective of immune memory in LTBI cells, as was hypothesized for the corresponding in vitro infection." (PMID 39918314, 2025). "We first validated that our L1210ImP-KO cells could not induce PSMB8, 9 and 10 following IFNγ stimulation and that their proliferation, oVSV production upon infection, IFNα and IFNβ production capacities and responses were similar to L1210ctrl cells." (PMID 40872920, 2025). "As a surrogate of SARS-CoV-2 antigen after infection, we used peptides covering the immunodominant sequence domains of the SARS-CoV-2 Spike (Peptivator peptide pool [Miltenyi]) to stimulate CD14-depleted PBMCs and measure IFNγ+ and CD107a+ frequencies in both CD4+ and CD8+ primary T cells." (PMID 40503889, 2025). "Finally, to understand the local inflammatory response following infection of non-lymphoid tissues, we evaluated gene expression of IFNG." (PMID 38389522, 2024). "As a first step toward identifying the cells in both the peritoneum and spleen that produce IFNγ in response to N. caninum, we infected Balb/C mice with 106 tachyzoites of N. caninum NC1 strain and used flow cytometry and intracellular cytokine staining on cells harvested at 10 h post-infection." (PMID 39445806, 2024). "Interestingly, C2-202 induced a much higher type I (IFNα1, IFNβ) and type III (IFNλ3), but not type II (IFNγ) response compared with TN/94-49 infection." (PMID 38315735, 2024). "Thus, IFNγ may trigger TNF production by astrocytes, which may self-sustain the inflammatory milieu, amplifying the Ser/5-HT-promoted infection of astrocytes by T. cruzi." (PMID 38776344, 2024). "Meanwhile, IFNγ production by PBMCs was undetectable in all groups in the absence of infection." (PMID 38712080, 2024).